TNF (tumor necrosis factor)
Diseases named in the same sentence as TNF in open-access papers (continued):
Sharing a sentence is not in itself a finding about the gene and the disease.
rheumatoid arthritis (continued). "Some studies suggest that Treg function is impaired in rheumatoid arthritis (RA) patients and treatment with anti-TNF-α antibodies restores it." (PMID 29541073, 2018). "Early studies on the pathogenesis of chronic inflammatory diseases, including rheumatoid arthritis, psoriasis, and inflammatory bowel disease, led to identification of TNF-α as a key trigger of innate inflammatory pathways." (PMID 30109481, 2018). "The chimeric monoclonal antibody, infliximab, which binds to TNF-α, is used clinically for treating rheumatoid arthritis and Crohn’s disease." (PMID 30301191, 2018). "Etanercept is a soluble TNFR2 decoy receptor that binds human or mouse TNF, and has shown efficacy in mouse models of rheumatoid arthritis (RA)." (PMID 29749399, 2018). "Although anti-PEG and anti-drug antibodies adversely affected efficacy of PEGylated uricase used in gout, the same was not true in large clinical trials of certolizumab pegol, a PEGylated anti-tumor necrosis factor Fab used in rheumatoid arthritis." (PMID 30405613, 2018). "It is likely that the anti-inflammatory effects of DXM can also be demonstrated in TNF-mediated inflammatory bone remodeling and rheumatoid arthritis." (PMID 29534535, 2018). "Anti-TNF biological therapy has been considered a breakthrough in the treatment of chronic autoimmune diseases, such as rheumatoid arthritis (RA)." (PMID 30314507, 2018). "Although TNF-α blockers first successfully treated rheumatoid arthritis, they were quickly extended to psoriasis and PsA." (PMID 30109481, 2018). "In rheumatoid arthritis or inflammatory bowel disease, TNFα blockade can successfully lead to clinically beneficial immune suppression." (PMID 30305177, 2018). "Adalimumab is a fully humanised immunoglobulin G1 (IgG1) monoclonal antibody to TNF-α that has been approved for the treatment of rheumatoid arthritis psoriatic arthritis, and psoriasis." (PMID 30914847, 2018). "SSB intake was also associated with IL-6 and TNF-α, and recent studies link SSB intake to the inflammatory disease rheumatoid arthritis." (PMID 29757229, 2018). "TNF-α contributes to many human autoimmune diseases by promoting the expansion and survival of T cells, including diabetes, rheumatoid arthritis, and psoriasis." (PMID 29335495, 2018). "Another observational study conducted in rheumatoid arthritis patients has found that serum vitamin D levels were negatively correlated with the levels of IL‐6 and TNF‐a." (PMID 29484258, 2018). "The introduction of drugs containing tumor necrosis factor-alpha (TNF-α) inhibitors has revolutionized treatments for many inflammatory diseases such as rheumatoid arthritis and inflammatory bowel disease." (PMID 29404710, 2018). "Genetic biomarkers are sought to personalize treatment of patients with rheumatoid arthritis (RA), given their variable response to TNF inhibitors (TNFi)." (PMID 29734345, 2018). "In rheumatoid arthritis, IL-1β and TNF-α produced by macrophages in the connective tissue stimulate the production of that MMP by articular chondrocytes." (PMID 30648118, 2018). "Tumor necrosis factor (TNF) inhibitor has been increasingly used in the treatment of inflammatory arthritis, including rheumatoid arthritis (RA) and ankylosing spondylitis (AS), with profound effect." (PMID 29975703, 2018). "But anti-TNF therapy of patients with active rheumatoid arthritis restored FOXP3 expression as well as suppressive function." (PMID 29619032, 2018). "In inflammatory lesions of humans with lupus or rheumatoid arthritis, miR-23b was found to be down-regulated, and it repressed TNF-α-induced NF-κB activation and inflammatory cytokine expression." (PMID 30314997, 2018). "Currently approved biological therapeutics for rheumatoid arthritis have four different modes of action: TNF inhibition, interleukin 6 receptor inhibition, T-cell co-stimulation blockade, and B-cell depletion." (PMID 29881431, 2018).
rheumatoid arthritis (continued). "In the KEGG enriched terms, ‘TNF signaling pathway’,‘Rheumatoid arthritis’, ‘MAPK signaling pathway’, and ‘IL-17 signaling pathway’ have shown to be associated with BRCA." (PMID 29671401, 2018). "The TWEAK/Fn14 interaction is particularly important in synovial inflammation associated with rheumatoid arthritis (RA); higher serum levels of TWEAK, TNF-α, and IL-6 have been reported in RA patients as compared to normal controls." (PMID 30576385, 2018). "The formula Du Huo Ji Sheng Tang effectively attenuates inflammation and promotes lymphatic drainage in the TNF-α-transgenic mouse model of rheumatoid arthritis (RA)." (PMID 30192890, 2018). "Therapeutic agents targeting TNF-α have been developed and used to treat patients with autoimmune arthritis, such as psoriatic arthritis, ankylosing spondylitis, and rheumatoid arthritis (RA)." (PMID 29534535, 2018). "In adults suffering from rheumatoid arthritis, increased levels of TNFα production coincides with higher rates of protein catabolism." (PMID 30541467, 2018). "Rheumatoid arthritis (RA) and hidradenitis suppurativa (HS) are autoimmune disorders that are mediated in part by overexpression of tumor necrosis factor-alpha (TNF-α)." (PMID 29614084, 2018). "TNF blockade is therapeutic in several progressive autoimmune diseases such as rheumatoid arthritis, ankylosing spondylitis, and inflammatory bowel disease." (PMID 29690885, 2018). "Increased TNF expression levels can be found at sites of inflammation in many autoimmune diseases, such as rheumatoid arthritis, Crohn’s disease, or psoriasis." (PMID 29295985, 2018). "TNFα antagonists have been developed for the treatment of rheumatoid arthritis (RA), psoriatic arthritis, juvenile idiopathic arthritis, ankylosing spondylitis, Crohn’s disease, and ulcerative colitis." (PMID 29518978, 2018). "One patient stopped tamoxifen due to side effects, and subsequently received an anti-tumour necrosis factor (anti-TNF)-α agent, adalimumab, for his rheumatoid arthritis and the AF decreased in size." (PMID 29785261, 2018). "A spinal transduction mechanism underlying rapid (24 hour) anti-nociceptive effects following anti-TNFα in IBD would also be consistent with the rapid reduction of pain reported in patients with rheumatoid arthritis." (PMID 29518097, 2018). "Elevated concentration of circulating TNF-alpha was detected in individuals with rheumatoid arthritis and the concentration increased following emotional stress." (PMID 30510499, 2018). "In particular, TNF blockade has become the benchmark in management of numerous chronic inflammatory diseases, such as rheumatoid arthritis, Crohn's disease, and psoriasis." (PMID 30555460, 2018). "Tumor Necrosis Factor-alpha (TNF-α) was reported to increase autophagy in rheumatoid arthritis human fibroblast-like synovial cell (RA-HFLS)." (PMID 30498756, 2018). "As a proinflammatory cytokine, tumor necrosis factor-alpha (TNF-α) plays a pivotal role in various autoimmune diseases such as rheumatoid arthritis (RA)." (PMID 29850502, 2018). "TQ has been showed effective in rheumatoid arthritis and the protective effects of TQ showed mediated via reduction in interleukins (IL-1β) and tumor necrosis factor (TNF-α) in adjuvant-induced arthritis, the major culprits of inflammatory responses." (PMID 28983249, 2017). "TNF-α antagonists represent a major therapeutic advance for the management of chronic inflammatory diseases, such as rheumatoid arthritis and psoriasis." (PMID 28179019, 2017). "At a hospital in central Taiwan, 407 patients with rheumatoid arthritis, ankylosing spondylitis, or psoriasis/psoriatic arthritis received anti-TNF therapy between 1 January 2004 and 30 June 2012." (PMID 29089055, 2017). "In contrast, pathway analysis revealed that inflammatory pathways such as TNF signalling pathway, rheumatoid arthritis and NF-κB signalling pathway were reduced after poly(I:C) stimulation in chronic cough ASMCs compared with healthy non-cough subjects." (PMID 28842514, 2017).
rheumatoid arthritis (continued). "Examples include antibodies to counteract the effects of TNF-α or IL-1β in inflammatory bowel disease, rheumatoid arthritis, psoriatic arthritis, ankylosing spondylitis, and atherosclerosis." (PMID 28487697, 2017). "ADAM17 inhibitors can inhibit tumor necrosis factor alpha (TNFα) shedding, and early inhibitors had efficacy in rheumatoid arthritis models." (PMID 29230082, 2017). "This is in agreement with guidance for the use of TNFα antagonists in rheumatoid arthritis, which demonstrated an increased proportion of detailed treatment and prescribing recommendations in consensus statements, as opposed to clinical guidelines." (PMID 28610621, 2017). "For example, vesicles derived from synovial fibroblasts of patients with rheumatoid arthritis (RA) have higher levels of a membrane-bound form of tumor necrosis factor (TNF) than vesicles from healthy control individuals." (PMID 28569211, 2017). "Biological agents against TNFα have been developed for the treatment of inflammatory diseases, including rheumatoid arthritis, psoriatic arthritis, axial spondyloarthritis, and inflammatory bowel diseases, such as Crohn’s disease and ulcerative colitis." (PMID 28124979, 2017). "Although OA is associated with metalloproteinase degradation of cartilage extracellular matrix components, rheumatoid arthritis is an inflammatory disease driven by proinflammatory cytokines, such as tumor necrosis factor (TNF) and IL-1." (PMID 28798097, 2017). "For instance, several studies have revealed that Tregs were functionally abnormal in patients with rheumatoid arthritis (RA), and TNF-α was the key mediator of this abnormal immune regulation." (PMID 28344516, 2017). "TNF‐α also is a major mediator in the development of chronic inflammation in diabetes mellitus and rheumatoid arthritis." (PMID 28572933, 2017). "A 65-year-old female with rheumatoid arthritis treated with a TNF-α inhibitor (Adalimumab) presented to her primary care physician with episodes of malaise, dyspnea, fever, weight loss and pleural effusions on and off for six months." (PMID 28086756, 2017). "This would be in keeping with studies highlighting TNF-alpha dysregulation as being key to a range of autoimmune disorders, such as rheumatoid arthritis." (PMID 29190674, 2017). "TNFα blocking antibodies are used to treat rheumatoid arthritis, inflammatory bowel disease and psoriasis, and this therapy is one of the biggest-selling pharmaceuticals in the world." (PMID 28432785, 2017). "In patients with rheumatoid arthritis, miR-223 appears to increase in response to anti-TNF treatment." (PMID 28460630, 2017). "Etanercept is a fusion protein that acts as a TNF inhibitor and is used in the treatment of rheumatoid arthritis, juvenile idiopathic arthritis (JIA), psoriatic arthritis, plaque psoriasis, and ankylosing spondylitis." (PMID 28357059, 2017). "Anti-tumor necrosis factor (anti-TNF) agents are often the first class of biologic drugs prescribed to patients with rheumatoid arthritis (RA), providing an effective therapeutic option that improves clinical, radiographic, and functional outcomes." (PMID 29246162, 2017). "TNF-α is a key cytokine implicated in apoptosis and inflammation, being its dysregulated production involved in rheumatoid arthritis or Crohn’s disease, where anti-TNF-α therapy is approved for clinical use." (PMID 28791020, 2017). "Excessive and deregulated expression of TNF not only plays a crucial role in various autoimmune diseases including rheumatoid arthritis and Crohn’s disease but is also efficiently targeted in the clinic with various TNF-neutralizing drugs." (PMID 29403470, 2017). "Blood samples were collected from 33 patients with rheumatoid arthritis before and 3 months after TNF-α blockade treatment." (PMID 28837666, 2017). "Neutralising antibody that targets TNF-α is currently used for rheumatoid arthritis in animal models and humans." (PMID 28265178, 2017).
rheumatoid arthritis (continued). "Trials on TNF for other inflammatory diseases, including Crohn’s disease, rheumatoid arthritis, and psoriasis, implicate TNF blockade in altering insulin sensitivity." (PMID 29163354, 2017). "The management of chronic inflammatory diseases, such as inflammatory bowel disease, psoriasis, and rheumatoid arthritis has significantly improved over the last decade with the clinical availability of anti-TNF-α biologics." (PMID 29312310, 2017). "The use of TNF-inhibitors and/or the IL-6 receptor antagonist, tocilizumab, in rheumatoid arthritis (RA) have pleiotropic effects that also involve circulating B-cells." (PMID 28886017, 2017). "Anti-TNFα therapy is currently in clinical use for inflammatory conditions, such as rheumatoid arthritis, the seronegative spondyloarthropathies, and inflammatory bowel disease." (PMID 28333114, 2017). "Anti-TNF-α therapy in rheumatoid arthritis inhibits germinal center reactions, thereby leading to decrease peripheral blood memory B cell levels, potentially contributing to a poor response to vaccination." (PMID 28784185, 2017). "TNF-α antagonists, like etanercept, adalimumab, and infliximab, are already used clinically for treating rheumatoid arthritis with dramatic efficacy." (PMID 28837666, 2017). "Some groups had reported that mice with rheumatoid arthritis receiving MSCs were less likely to show signs of joint inflammation than those not receiving MSCs by decreasing proinflammatory cytokines such as TNF-α and IL-6." (PMID 29096724, 2017). "Ca-gluconate has been shown to reduce expression of pro-inflammatory cytokines IL-6 and TNF-α, as well as myeloperoxidase levels in both burn and rheumatoid arthritis mouse models." (PMID 28604843, 2017). "A previous report revealed that TNF-α reduced galectin-3 protein expression as measured by flow cytometry in human OA and rheumatoid arthritis synovial fibroblasts 18 hours following exposure to TNF-α." (PMID 29096716, 2017). "TNFα is an important target for the treatment of inflammatory diseases, such as rheumatoid arthritis and inflammatory bowel diseases." (PMID 28124979, 2017). "TNF-α is a master cytokine for the inflammatory response, contributing to different inflammatory conditions, and therapeutics blocking TNF-α signaling are approved drugs for the treatment of rheumatoid arthritis or Crohn’s disease." (PMID 28791020, 2017). "Dual inhibition of TNF-α/IL-17 is efficacious to reduce signaling redundancy in rheumatoid arthritis." (PMID 29137228, 2017). "In patients with rheumatoid arthritis, anti-TNF therapy has been incredibly effective in treating disease, response to this therapy is associated with the induction of Treg that can secrete IL-10 and TGFβ to control inflammatory responses." (PMID 29176976, 2017). "Excessive inflammation, often triggered by the uncontrolled release of TNF, can lead to rheumatoid arthritis, cancer and many other diseases." (PMID 28432785, 2017). "ETN, a licensed biologic, has been used for TNF-α blockade for over 20 years and has shown remarkable efficacy as an anti-inflammatory agent in rheumatoid arthritis and inflammatory bowel diseases; its safety profile is well known." (PMID 29190292, 2017). "Monoclonal antibodies against TNFα, including infliximab, adalimumab, golimumab, and certolizumab pegol, are widely used for the treatment of the inflammatory diseases such as rheumatoid arthritis and inflammatory bowel disease." (PMID 28124979, 2017). "In our study, to increase the proliferation of synovial MSCs, TNFα is effective at 25 ng/ml, which is approximately 100 times higher than in the synovial fluid of rheumatoid arthritis patients." (PMID 28542363, 2017). "Previously, it was shown that the periodontal status of rheumatoid arthritis patients receiving anti-TNF-α treatment stabilized as a side-effect of treatment." (PMID 29163477, 2017).
rheumatoid arthritis (continued). "Although an increasing amount of antirheumatic agents exist, the most commonly used in the treatment of rheumatoid arthritis is the group of inhibitors of tumor necrosis factor-α (TNF-α)." (PMID 28824542, 2017). "During rheumatoid arthritis (RA), Tumor Necrosis Factor (TNF) activates fibroblast-like synoviocytes (FLS) inducing in a temporal order a constellation of genes, which perpetuate synovial inflammation." (PMID 28708839, 2017). "The present study established an experimental model of IL-17-producing cells polarized from human CD4+ cells and broadened our knowledge of the mechanism of TNF-α inhibitors in rheumatoid arthritis treatment." (PMID 27926504, 2017). "Inappropriate production of TNF has been implicated in the pathogenesis of a variety of human diseases, including sepsis, diabetes, cancer, osteoporosis, allograft rejection, multiple sclerosis and rheumatoid arthritis (RA), including pulmonary fibrosis." (PMID 28629363, 2017). "TNF-α plays a key role in the development of rheumatoid arthritis (RA) and inflammatory bone loss." (PMID 28771604, 2017). "Recently, TNF antagonists have been increasingly used in the treatment of chronic inflammatory diseases such as rheumatoid arthritis (RA), ankylosing spondylitis (AS), psoriasis, and inflammatory bowel disease." (PMID 28743918, 2017). "In CKD, circulating levels of TNFα are well within the range found in rheumatoid arthritis patients treated with infliximab." (PMID 28333114, 2017). "KEGG analysis identified the pathways "rheumatoid arthritis", "NF-kappa B signaling pathway", "malaria" and "TNF signaling pathway" as significantly affected by hypoxia/reoxygenation." (PMID 28046118, 2017). "TNF-α neutralization (infliximab) has been used successfully in several inflammatory pathologies including rheumatoid arthritis, psoriasis arthritis, ulcerative colitis, and Crohn’s disease." (PMID 28184367, 2017). "This was studied in rheumatoid arthritis (RA) synoviocytes stimulated with IL-17A and tumor necrosis factor alpha (TNF-α), which act synergistically to induce a massive inflammatory signal." (PMID 28620392, 2017). "Its expression is significantly higher in the synovial fluid of patients with rheumatoid arthritis and in psoriatic skin and this overexpression is abrogated by treatment with dexamethasone, methotrexate, or by TNF-α inhibition." (PMID 28301468, 2017). "A more recent clinical target to attempt to control rheumatoid arthritis is tumor necrosis factor (TNF)." (PMID 29270905, 2017). "Another example is the semi-direct link through the Tumor Necrosis Factor (TNF) and its receptor in the superfamily 1B (TNFR1B), associated with rheumatoid arthritis and asthma, respectively." (PMID 28740175, 2017). "GPI is closely related to the development of rheumatoid arthritis and is capable of stimulating the cytokine activity of TNF-α and IL-1β." (PMID 28384257, 2017). "Plasma levels of the inflammatory cytokine tumor necrosis factor alpha (TNFα) are increased in age-related and chronic conditions such as atherosclerosis, rheumatoid arthritis, psoriasis, and Crohn’s disease." (PMID 28045034, 2017). "The risk of myocardial infarction is markedly reduced also in patients with rheumatoid arthritis who respond to anti-TNF-α therapy." (PMID 28460644, 2017). "Tumor necrosis factor antagonist inhibitors have transformed the approach to patients with severe autoimmune conditions, such as rheumatoid arthritis." (PMID 28086756, 2017). "Here, we report a case of concomitant disseminated histoplasmosis and tuberculosis in a 65-year-old female with rheumatoid arthritis treated with TNF-α inhibitor." (PMID 28086756, 2017). "In the case of our experiments, the pathologic process is high levels of TNF-α, which is also seen in rheumatoid arthritis." (PMID 27450561, 2016).